ATG5 (autophagy related 5)
Diseases named in the same sentence as ATG5 in open-access papers (continued):
Sharing a sentence is not in itself a finding about the gene and the disease.
breast carcinoma (continued). "In this work, Rg5 induced autophagy in breast cancer cells, which was demonstrated by the formation of autophagosomes observed by TEM, the upregulation of LC3-II, Beclin-1, Atg5, and Atg12 expression and the downregulation of p62 expression." (PMID 31963684, 2020). "We also found that LA can increase autophagy through regulation of ATG5, LC3B, and Beclin 1 expression, influencing the proliferation of MDA-MB-231 breast cancer cells." (PMID 30841634, 2019). "To further evaluate the effect of ATG5-dependent macroautophagy on the CMA-mediated growth and metastasis of human breast cancer cells, we transfected tumor cells with ATG5 siRNA and evaluated their growth and metastasis." (PMID 28684853, 2017). "Silencing of Sirt3 expression decreased autophagy in human breast cancer cells exposed to hypoxia, as indicated by an increase in p62 protein level, and decreases in LC3 and Atg5–12 proteins." (PMID 27270321, 2016). "ATG5-depleted cells showed a remarkable increase in their sensitivity to CTet compared to control siRNA- or non-transfected cells, thus suggesting that autophagy could represent a safeguard mechanism initially activated by breast cancer cells to counteract CTet-mediated cellular stress." (PMID 22905241, 2012). "We also show that autophagy markers Atg5, Atg12, and LC3-B are expressed in these dormant stem cell-like breast cancer cells." (PMID 22046561, 2011). "In contrast, genetic depletion of BECN1, ATG5, p62/SQSTM1, or LAMP1 or pharmacological inhibition by chloroquine, resensitizes breast cancer cells to PARPi by shifting DNA repair towards error‐prone NHEJ (non‐homologous end joining), leading to mitotic catastrophe and genomic instability." (PMID 41329030, 2025). "Furthermore, chemoresistant breast cancer cells exhibited elevated autophagy levels, and ectopic expression of BRMS1L significantly suppressed protective autophagy through downregulating ATG5." (PMID 41282485, 2025). "Furthermore, we blocked autophagy by knocking down ATG5, and demonstrated that ATP6AP1 stimulates luminal breast cancer cell proliferation and TAM resistance through autophagy activation." (PMID 40133274, 2025). "In this study, we demonstrate that ERBB2 promotes autophagy by upregulating ATG12 as well as other autophagy-related (ATG) proteins including ULK1, FIP200, ATG5, and ATG7, leading to breast cancer treatment resistance and worse outcome to patients with ERBB2-positive breast cancer." (PMID 33801244, 2021). "Similarly, in the ADR-induced dormancy model of Neu-driven breast cancer, mice that were i.v. injected with ADR-treated Atg5 knockdown cancer cells developed lung metastasis significantly sooner than those that were injected with wild-type dormant cells." (PMID 33816262, 2021). "Among them, Atg5 is an important gene in mammalian autophagy, serving as a key promoter of early autophagy.To determine whether ATP6AP1 promotes luminal breast cancer cell proliferation and TAM resistance through autophagy activation, we blocked autophagy by knocking down ATG5 using specific shRNA." (PMID 40133274, 2025). "In the clinical treatment of breast cancer, H3K27ac modification-induced upregulation of lncRNA ZNF649-AS1 gene may lead to autophagy and trastuzumab resistance by binding to PTBP1 and promoting ATG5 transcription." (PMID 36635500, 2023). "Furthermore, there is a growing body of literature that recognizes the importance of potential applications of autophagy related proteins, including LC3, ATG7, ATG5, Beclin1, and SH3GLB1, as prognostic biomarkers in some tumors, like glioma, breast cancer, and colon cancer." (PMID 33510635, 2020). "In addition, we performed stratified analyses by the clinical characteristics including age, family history of breast cancer, axillary lymph node status, TNM stage, tumor grade, and vascular invasion to further clarify the prognostic value of ATG5 rs473543 genotypes in TNBC patients." (PMID 29382381, 2018).
breast carcinoma (continued). "Here, our experimental results illustrated that LC3 and LC3B expression, LC3-II/I, ATG5 and ATG7 protein levels were increased, p62 expression and protein level were reduced after PDK4 was depleted in MCF-7 cells, suggesting that PDK4 interference might stimulate autophagy in breast cancer cells." (PMID 38678126, 2024). "In breast cancer, miR-567 could inhibit cancer cell proliferation and migration by regulating KPNA4; miR-567 could also regulate autophagy and reverse trastuzumab resistance via ATG5 in breast cancer; in renal cell carcinoma, miR-567 could inhibit cancer cells progression by regulating PRDX3." (PMID 34226531, 2021). "Autophagy is required for the hemostasis of cell to prevent tumorigenesis, and absence of autophagy master genes, such as Beclin-1, ATG5, and UVRAG, has been reported in multiple cancers including breast cancer lung cancer." (PMID 34475961, 2021).
melanoma (74 papers, 2013 to 2025). A malignant, usually aggressive tumor composed of atypical, neoplastic melanocytes. "Their study revealed a significant association between ATG5 expression levels in melanoma samples from patients and progression-free survival, indicating that higher ATG5 levels in tumors were associated with a more favorable outcome." (PMID 39371094, 2024). "ATG5 is an important protein in early autophagy formation, and ATG5 deficiency in melanocytes is associated with oncogene-dependent senescence-promoting melanoma tumorigenesis." (PMID 37138798, 2023). "The finding that the expression of RELB is upregulated in Atg5‐deficient TECs isolated from melanoma‐bearing mice, suggests a transcriptional mechanism." (PMID 38009521, 2023). "A heterozygous loss of ATG5 enhanced melanoma metastasis and predicted poor overall patient survival." (PMID 32340261, 2020). "Of note, as for the Atg7-deficient BrafV600E; Pten−/− driven melanomas, complete loss of Atg5 reduced tumor formation." (PMID 31998652, 2019). "Primary melanoma cells also display reduced expression levels of ATG5, a factor which was associated with a worse prognosis." (PMID 27896217, 2016). "Notably, reduced ATG5 expression has been confirmed to be closely associated with shortened progression-free survival in early-stage melanoma patients." (PMID 40497999, 2025). "In line with this notion, additional findings showed that hemizygous loss of ATG5 occurred during melanoma progression, and reduced expression of ATG5 and ATG7 was observed in both primary and metastatic melanoma tissues likely due to deficiency of nuclear respiratory factor (NRF1)." (PMID 36670319, 2023). "Additionally, decreased ATG5 levels in primary melanomas compared to benign nevi were significantly linked with poor progression-free survival in a group of patients with early stage cutaneous melanoma." (PMID 35370701, 2022). "Furthermore, the analysis of survival data of melanoma patients revealed an association between reduced ATG5 and ATG7 levels with an unfavourable clinical outcome." (PMID 34458153, 2021). "In turn, downregulation of ATG5 in WNT5ahigh melanoma cells was associated with lower level of WNT5a and increased level of β-catenin, supporting the conclusion that autophagy is inversely correlated with the activity of canonical WNT/β-catenin signaling pathway." (PMID 32340261, 2020). "While it is unknown if ATG16L1 likewise possesses pro-apoptotic activity, hemizygous ATG5 deletions and ATG5 mRNA downregulation in human melanomas are associated with metastasis and poor patient survival." (PMID 31636955, 2019). "Furthermore, when autophagy was inhibited in melanoma cells by either ATG5 or p62/SQSTM1 deficiency or CQ treatment, melanoma cells could recruit NK cells into the tumor site by CCL5 releasing." (PMID 36300110, 2022). "However, the influence of ATG5 genotypes on cancer prognosis remains largely unexplored, and only one study suggested that heterozygous loss of ATG5 was associated with resistance to anticancer treatment and metastasis risk in melanoma patients." (PMID 29382381, 2018). "In the present study, DIOS significantly promoted the formation of autophagolysosome vacuole and enhanced LC3II/I and Atg5 expression while inhibiting p62 expression, indicating its impact on autophagy in melanoma cells." (PMID 39844566, 2025). "The knockout of ATG5 or ATG7 significantly inhibited the survival of melanoma cells under low-nutrient conditions." (PMID 40497999, 2025). "Compared with a benign nevus, Atg5 is frequently downregulated in primary melanoma, reducing basal autophagy as indicated by decreased LC3." (PMID 39844566, 2025). "Decursinol angelate is a coumarin compound that inhibits autophagy in melanoma B16-F10 cells by inhibiting ATG5, ATG7, and Beclin 1 expression and LC3-I to LC3-II conversion." (PMID 39371094, 2024). "The survival of melanoma cells in acidic environments was reduced when autophagy was inhibited by ATG5 silencing." (PMID 39371094, 2024).
melanoma (continued). "In 2013, Liu et al38 demonstrated that during the early stages of malignant transformation in skin cancers, such as melanoma, autophagy was diminished compared with that in normal melanocytes, correlating with downregulated ATG5." (PMID 39371094, 2024). "Atg5 not only mediates a positive feedback loop between the Wnt signaling pathway and autophagy in melanoma cells, but also regulates cell polarity and movement through the activation of the RhoA and Jun N‐terminal kinase (JNK) signaling cascades." (PMID 38826147, 2024). "A low expression of LC3‐II representing low autophagy activity in melanoma was reported, and overexpression of Atg5 increased autophagy activity accompanied by decreased cell proliferation and colony formation." (PMID 38826147, 2024). "3′-Hydroxydaidzein is an ortho-dihydroxyisoflavone that upregulates ATG5 expression to enhance autophagy in melanoma." (PMID 39371094, 2024). "Conversely, autophagy inhibition with either hydroxychloroquine or inducible shRNA against ATG5 resulted in significantly augmented temozolomide-induced cell death in aggressive melanoma spheroids." (PMID 38336727, 2024). "We then injected B16‐F10 melanoma in Atg5+/+ mice, Atg5/STING+/+, Atg5BECKO, and Atg5/STINGBECDKO mice, monitored tumor growth and inspected the TEC phenotype by immunofluorescence for the presence of proinflammatory/immunomodulatory factors." (PMID 38009521, 2023). "ATG5 was previously documented to assume a critical role in a positive feedback loop between Wnt signaling and autophagy in melanoma." (PMID 35194023, 2022). "Nevi can progress to melanoma if the senescent barrier is breached and downregulation of ATG5 prevents oncogene-induced senescence in primary human melanocytes." (PMID 33664481, 2021). "We have recently shown that several proteins involved in the autophagic process; ATG5, Beclin-1 and BIF-1 are reduced in melanoma patients and that reduction of ATG5 and BIF-1 is associated with a less favourable patients’ outcome." (PMID 34458153, 2021). "Concerning the efficient suppression of zinc-induced damage by downregulation of Atg5 protein in exposed melanoma cells, the active role of this gene is clearly confirmed in the present model." (PMID 33440911, 2021). "Next, we detected a consistent decrease in ATG7 expression from benign nevi to primary melanomas and in contrast to ATG5, the levels of ATG7 were further reduced in metastatic tissues." (PMID 34458153, 2021). "We demonstrate that the expression of ATG7 is reduced in primary melanoma and in contrast to ATG5, the expression of ATG7 is further reduced in metastatic melanoma tissues." (PMID 34458153, 2021). "Our data support a tumour preventive role in the early stages of melanoma development, and a previous study has shown that ATG5 is down-regulated at this stage of human melanoma resulting in enhanced proliferation and bypass of senescence." (PMID 33664481, 2021). "In fact, ATG5 is downregulated in melanoma tissues and the reduced expression correlated with poor outcome for patients." (PMID 34458153, 2021). "Specific Atg7 and Atg5 ablation of BRAFV600E-driven melanoma inhibits tumour formation and induces melanocyte senescence in GEMMs." (PMID 33802014, 2021). "In agreement with our previous results, we observed a significant decrease in ATG5 levels from benign nevi to primary melanomas." (PMID 34458153, 2021). "To further validate that ectopic expression of HopQ induces autophagy in melanoma cells, leading to suppressed vimentin expression, we disrupted autophagy by silencing ATG5 and ATG7 with siRNA." (PMID 32286254, 2020). "In melanoma cells cultured in vitro, activation of ATG5 reduced proliferation and induced senescence." (PMID 31417903, 2019). "Strikingly, hemizygous deletion of Atg5 enhances melanoma growth (compared to Atg5+/+ or Atg5−/−), metastatic power and resistance to targeted therapy, such as BRAF inhibitor." (PMID 31998652, 2019).
melanoma (continued). "In studies with melanoma and non-small cell lung cancer, Atg5 was shown to play an antitumor role especially in early carcinogenesis In contrast, in pancreatic cancer, autophagy is actually required for tumorigenesis de novo." (PMID 30742638, 2019). "In this context, heterozygous deletion of Atg5 in genetically engineered mice enhanced melanoma metastasis and worsened the response to dabrafenib." (PMID 30254376, 2019). "In particular, melanocyte-specific Atg7 or Atg5 ablation can prevent melanoma formation and drive melanocytic senescence in the same GEMM model, being the Atg7-related phenotype associated with increased oxidative stress and extended survival rate." (PMID 31998652, 2019). "A decrease in ATG5 expression, a key regulator of autophagy, reduced survival rate in 158 primary melanoma patients, and decreased ATG5 expression promotes cancer-cell proliferation and is associated with the progression of early stage cancer." (PMID 30400561, 2018). "Our previous work showed a downregulation of ATG5 and autophagy in melanoma and provided evidence that enforced downregulation of ATG5 accelerates cell proliferation by delaying oncogene-induced senescence." (PMID 30245976, 2018). "During the development of many cancers, including colorectal cancer and melanoma, ATG5 is often downregulated." (PMID 29666625, 2018). "By RNA interference technique, it was demonstrated that shATG5 #1 and #2 plasmids' transfection were workable to the basal ATG5 mRNA and protein expression levels in B16-F10 melanoma cells." (PMID 30062060, 2018). "In another study, knockdown of ATG5 in melanoma cells decreased cells’ capacity to survive metabolic stress and to colonize lungs in mice following intravenous injection." (PMID 28459042, 2017). "ATG5 knockdown in B16-F10 melanoma cells increased tumor vessel tortuosity; on the other hand, endothelial cell-specific deletion of ATG5 led to the formation of smaller and less mature tumor vasculature with endothelial cell lining and perfusion defects." (PMID 28459042, 2017). "We examined five single‐nucleotide polymorphisms (SNPs) in three ATG genes (ATG5;ATG10; and ATG16L) with known or suspected impact on autophagic flux in an international population‐based case–control study of melanoma." (PMID 27748080, 2016). "Induction of autophagy by ectopic ATG5 expression or autophagy inducers attenuated clonogenic growth of melanoma cell lines harboring low ATG5 levels." (PMID 27896217, 2016). "One study reported that ATG5 is often downregulated in human melanomas compared to preneoplastic nevi, and that low ATG5 expression is an adverse prognostic indicator in melanoma." (PMID 27655644, 2016). "ATG5, a key regulator of autophagy, was found to be downregulated in primary melanomas compared to benign nevi, and this decrease in ATG5 expression is accompanied by a reduction in the expression of LC3 and in basal autophagy." (PMID 25743109, 2015). "It was shown that patients expressing low levels of ATG5 in their tumors exhibited decreased progression-free survival according to a follow-up of 158 primary melanoma patients." (PMID 25743109, 2015). "A key autophagy protein ATG5 is reportedly downregulated in primary melanoma compared to nevi, and early stage melanomas with low ATG5 levels have worse prognosis." (PMID 24743024, 2014). "Our results show that genetic inhibition of autophagy through knockdown of the additional essential autophagy components Atg7 and Atg5 impaired melanoma cell growth in multiple cell lines, demonstrating the reliance upon autophagy for survival." (PMID 23383069, 2013). "While activation-induced cell death and in vitro suppressive activity of Treg cells were not affected, ATG5 deficiency in CD4+ T cells led to increased anti-tumor responses against melanoma." (PMID 40977681, 2025).